MTOR (mechanistic target of rapamycin kinase)
Diseases named in the same sentence as MTOR in open-access papers (continued):
Sharing a sentence is not in itself a finding about the gene and the disease.
cancer (continued). "Besides phosphatases and tensin homolog (PTEN)/PI3K/Akt/mTOR, Janus kinase (JAK)/STAT and Ras/Raf/mitogen-activated protein kinase (MEK)/ERK/MAPK signaling pathways are also interconnected with the modulation of inflammation, oxidative stress, and cancer cells survival." (PMID 36984763, 2023). "By further examining changes in the PI3K/AKT/mTOR pathway looking at the downstream transcription factors S6K and eIF4E, and PRAS40 (inhibits mTOR and IRS-1), we could identify their role in the negative feedback of the PI3K pathway, an effect commonly seen in various cancers and cancer models." (PMID 37908840, 2023). "In addition, simultaneous inhibition of mTOR and ERK1/2 could further increase the accumulation of ROS in tumor cells, suggesting a synergistic effect of combined mTOR and ERK1/2 inhibitors for cancer therapy." (PMID 37304865, 2023). "However, mTOR inhibitors may have both pro- and anti-inflammatory actions and prompt both initial stimulation of Type 1 T helper (Th1) CD4+ T cells as well as long-term expansion of Tregs in cancer." (PMID 36139669, 2022). "Furthermore, there is no study between mTOR inhibitor and cuproptosis in cancer." (PMID 36209249, 2022). "Functional investigation of hub genes revealed that they could activate TSC/mTOR pathway, ER hormone, EMT, RTK pathway, RAS/MAPK pathway, and PI3K/AKT pathway but inhibit cell cycle and apoptosis, which indicated the predominant role of our hub genes in cancer progression and metastasis." (PMID 35769483, 2022). "Previous studies have reported that HIF inhibits mTOR activity through the transcriptional induction of antagonists of mTOR signaling, raising a question as to whether the use of mTOR inhibitors constitutes a rational approach to the treatment of VHL-defective cancer." (PMID 36097292, 2022). "Indeed, different works have highlighted the key role of SOCE in promoting the migration of different cancer cell lines, such as chemoresistant IGROV1 ovarian cancer cells by regulating focal adhesion turnover, SW480 colorectal carcinoma cells and oral cancer cells through Akt/mTOR/NF-κB signalling." (PMID 35806388, 2022). "Targeting the ERK pathway in cancer cells is not simple because cells develop resistance by activating compensatory feedback loops such as the phosphatidylinositol-3-kinase (PI3K)—protein kinase B (Akt)—mammalian target of rapamycin (mTOR) (Akt/mTOR) signaling." (PMID 36364072, 2022). "However, it was not proved that mTOR level correlates with cell sensitivity to its inhibitors; therefore, experimental confirmation of cancer cell response to drugs might be needed to predict patient outcome in case of mTor inhibitors." (PMID 35163092, 2022). "Therefore, the PI3K–Akt–mTOR pathway could represent an attractive target for reversing the negative effects of metabolism and immunity in cancer." (PMID 34885023, 2021). "Similarly, pathway analysis classified genes regulated by EGCG as being involved in steroid biosynthesis, pathways in cancer, chemokine signaling, TGF-beta signaling, cytokine-cytokine receptor interaction, MAPK signaling, IL-17 signaling, insulin secretion, FoxO signaling, and mTOR signaling." (PMID 34881283, 2021). "In the case of HNSCC, activation of the PI3K/mTOR signaling circuitry is the most frequently dysregulated signaling pathway, and this reliance on PI3K/mTOR signaling for tumor growth may in turn expose a key cancer vulnerability that can be exploited therapeutically." (PMID 33888713, 2021). "The use of a transgenic mouse model for cancer xenotransplantation has confirmed that a lack of SIRT4 can accelerate the progression of cancer cell death in various cancers by regulating glutamine metabolism in the mitochondria or the mammalian target of rapamycin (mTOR) pathways." (PMID 34335684, 2021).
cancer (continued). "Moreover, genistein-mediated suppression of mTOR increases dephosphorylation and the subsequent nuclear translocation of TFEB, which is associated with a significant increase in lysosomal content and activity in treated cancer and non-cancerous cells." (PMID 34575981, 2021). "In addition, analyzing data from The Cancer Genome Atlas, the expression profiles of HRH1 and TSC2 were found to be negatively correlated (PCC = −0.15, P = 2 × 10‐6) and, conversely, HRH1 expression was found to be positively correlated with the canonical lung‐metastasis signature and mTOR pathway." (PMID 34378323, 2021). "In addition, NSC765598 displayed favorable properties as a drug lead compound and thus could be considered a novel small molecule with potential for multi-target inhibition of EGFR/iNOS/mTOR/TGFB1/FGFR/MAP2K1 and could serve as a lead compound for developing new therapeutics for cancer treatment." (PMID 33842373, 2021). "The coadministration of TPA and EGCG in cancer model systems might be a promising approach to promote both the synergic inhibition of AR signalling mediated by the LMTK2 inhibitory action and the down regulation of PI3K-Akt-mTOR pathway directly by means of EGCG." (PMID 34064250, 2021). "Furthermore, GL reduced phosphorylated GSK-3β (p-GSK-3β), but increased phosphorylation of Akt on serine 473 (p-Akt), possibly due to a negative feedback mechanism, as observed earlier in various cancer cell lines treated with mTOR inhibitors such as everolimus and rapamycin." (PMID 34091442, 2021). "PPARγ agonists may also act as negative regulators of cancer growth by the interaction with the IGF system and its down-stream pathways, such as mitogen-activated protein kinase (MAPK), phosphoinositide 3-kinase (PI3K), and the mechanistic target of rapamycin (mTOR) pathways." (PMID 34067944, 2021). "Besides, based on the analysis of cancer-related processes and pathways, KCNK family genes were involved in the activation or suppression of cell cycle, DNA damage response, epithelial-mesenchymal transformation, hormone AR/ER, PI3K, MAPK, RTK and mTOR signaling pathways." (PMID 32742463, 2020). "Besides, the EDF genes within subtype 1 were enriched in functions of cell growth, such as "ERBB2 signaling pathway" and "Constitutive Signaling by Aberrant PI3K in Cancer", which could affect tumor cell growth, proliferation, and migration by perturbing the PI3K/AKT/mTOR signaling pathway." (PMID 33078899, 2020). "The exact mechanism of action of AZD2014 in live human cancer cells is yet unclear and warrants further investigation as studies have demonstrated that AZD2014 may bind directly to the kinase domain of mTOR while other studies have shown mTOR complex dissociation with AZD2014 treatment." (PMID 33142217, 2020). "In conclusion, this study reinforces our previous suggestion that the combination of palbociclib with PI3K/mTOR inhibitors may represent a valuable therapeutic strategy for MPM treatment, highlighting its efficacy as a novel approach for targeting distinct metabolic features of MPM cancer cells." (PMID 32708306, 2020). "In addition, the development of drugs targeting the PI3K/AKT/mTOR or AMPK pathways for TNBC treatment described herein are a gradually developing field in which the efficacy and toxicity of new agents, in addition to their interactions with different cancer pathways, should be considered." (PMID 32587770, 2020). "Importantly, mTOR activation has also been reported to enhance glycolytic traits of the resistant cells, suggesting that glycolytic function may be under PI3K/mTOR signaling control in cancer and other pathologies." (PMID 32164162, 2020).
cancer (continued). "Some studies have suggested that local anaesthetics stimulated apoptosis of cancer cells may be unrelated to the sodium-channel blockade, while in other studies have reported that the role of local anaesthetics is to inhibit the transduction of the PI3K/Akt/mTOR signal pathway." (PMID 31300048, 2019). "In particular, DNA strand-breaking, activation of protein phosphatase 2C, abrogation of STAT3 signaling and the PI3K/Akt/mTOR pathway, transformation of mitochondria and uncoupling of oxidative phosphorylation, as well as inhibition of SIRT may account for cytotoxic and anti-cancer properties of GA." (PMID 31379572, 2019). "The suppression of PI3K/Akt/mTOR and NF-κB pathways in MDA-MB-231 cells could be a potential molecular mechanism to elucidate the anti-metastatic effects of alisol A. Finally, recent studies have demonstrated that autophagy may exert suppressive effects in cancer metastasis." (PMID 31658635, 2019). "Although mEAK-7 protein levels appear to be disproportionately high in human cancer cell lines when compared with non-cancerous cells, this limited observation does not exclude the possibility that mEAK-7 is present in healthy human tissues, because mTOR expression is found in many tissue types." (PMID 31288154, 2019). "The study suggests that single mTOR inhibitors may not be an ideal choice for treating cancer." (PMID 31228948, 2019). "Thus, mEAK-7 protein and activated mTOR signaling was found to be enhanced in primary NSCLC, and substantially detected in metastasized lymph nodes, suggesting that mEAK-7 could function as a biomarker for patients with metastasized cancers." (PMID 31288154, 2019). "Furthermore, several studies also indicated that stimulation of OX1R can mediate glucose metabolism through stimulating HIF-1α signaling and PI3K/Akt/mTOR pathways in human hepatocellular carcinoma cells, suggesting that orexin-A/OX1R might be a potential target for malignant cancer therapy." (PMID 30429828, 2018). "Thus, MEK and mTOR co-targeting may represent a successful, generalized targeting strategy against diverse BRAF-fusions that warrants careful testing in PLGGs as well as other pediatric and adult cancers where additional BRAF-fusions are being discovered." (PMID 29156677, 2017). "Hence, mTOR inhibitors used as monotherapy do not provide the expected anti-cancer efficacy." (PMID 29104248, 2017). "Thus, Rac may drive both the AKT/mTOR and MEK/ERK pathways only in select subtypes of cancer cells, making Rac a promising therapeutic target that could supplant that need for drug combinations targeting individual components of both the PI3K/AKT/mTOR and MEK/ERK pathways." (PMID 28423521, 2017). "Additionally, the reduction in miR-199a-3p expressions and thereby non-suppression of mammalian target of rapamycin (mTOR) could result in advanced forms of cancers." (PMID 28881744, 2017). "Interestingly, proteomics has played a lead role in mapping cancer signaling pathways and has successfully delineated the break point cluster region (BCR)-ABL1, extracellular signal-regulated kinase (ERK) pathways, and mechanistic target of rapamycin (mTOR) pathways." (PMID 29068423, 2017). "Whether PRAS40 mediates signaling independent of mTOR inhibition in cancer cells remains elusive." (PMID 28945219, 2017). "Besides, AURKA could contribute to cancer cell survival via increasing anti-apoptotic modulators (Bcl-2, MCL-1) and decreasing pro-apoptotic regulators (Bax, Bim, PUMA) or suppressing autophagy through activating mammalian Target of Rapamycin (mTOR) signaling." (PMID 28147341, 2017). "Previous studies targeting mTOR signaling in cancer have focused on allosteric inhibition of mTORC1, but not mTORC2; therefore, the anticancer activity may be attributed to incomplete inhibition of the mTOR pathway." (PMID 27031247, 2016).
cancer (continued). "The unique ability of DIF-3 to inhibit the mTOR pathway and to induce non-apoptotic cell death is potentially of great interest in cancer therapy because cancer cells often display defects in apoptosis, and targeting other modes of cell death could contribute to eradicating tumor cells." (PMID 27027430, 2016). "Thus, our results reveal that besides its PTEN-dependent anti-cancer effects, PICT-1 can also exhibit tumor suppressor function by triggering a pro-death autophagic process which is involves rRNA transcription inhibition and the inactivation of the AKT/mTOR/p70S6K transduction pathway." (PMID 27729611, 2016). "Interestingly, concomitant knocking down of PCK1 and not G6PC along with mTOR pathway could overcome the inhibition of cancer cell proliferation and survival." (PMID 27551450, 2015). "Given that cells overexpressing PRL-3 exhibit shared characteristics with cells possessing hyperactive PI3K/Akt/mTOR signalling, including enhanced cell proliferation, survival, and motility, we hypothesized that PRL-3 might potentially play a role in mTOR regulation, as well in cancer progression." (PMID 26597054, 2015). "Hence it is not surprising that elevated mTOR signaling has been detected in several cancers." (PMID 26255626, 2015). "Additionally, mTOR and MEK inhibition may alter the interaction between tumor and other immune or stromal cells, such as cancer-associated fibroblasts, that were not evaluated here." (PMID 26506415, 2015). "In addition, it has been shown that mTOR is important for the oncogenic transformation induced specifically by PI3K and Akt, components of a pathway that has also been indicated to be involved in tumorigenesis, which is becoming an important target for cancer treatment." (PMID 25009644, 2014). "Moreover, the existence of a controversy in the literature as to whether ALDH+ cells isolated from cancer cell lines can serve as in vitro model for CSC study, further indicates the need to study the effect of mTOR inhibition using alternative methods to identify and characterize CSCs." (PMID 24185040, 2013). "Since growth factor (e.g., IGF-I) and nutrient (e.g., amino acids) reductions extend lifespan and reduce cancer, and mTOR integrates responses, it was proposed that mTOR is central to the aging process and its chronic inhibition might delay or reduce the severity of cancer." (PMID 22680924, 2012). "PI3K/Akt signaling is facilitated by mammalian target of rapamycin (mTOR), and hyperactivation of this pathway in LMS has been repeatedly reported in human samples suggesting that markers such as phosphoAkt may become useful in distinguishing benign from malignant neoplasms." (PMID 22448121, 2012). "Collectively, results suggested that glucose metabolism of tumor cells relies on mTOR activity and 4E-BP1 phosphorylation to sustain Mcl-1 protein translation, and that diminished expression of Mcl-1 through the disruption of aerobic glycolysis may sensitize cancer cells to apoptosis." (PMID 22680924, 2012). "Molecular targets including phosphorylated Akt, cyclinD1, mTOR, and androgen receptor are down-regulated by the combination of curcumin and resveratrol due to the activation of PTEN, suggesting that some herbs may reduce cancer incidence due to the PTEN function." (PMID 23213333, 2012). "The relatively short half-life of everolimus may result in short-lived inhibition of mTOR signalling at low doses, which may be sufficient to alter FDG uptake, but insufficient to induce detectable differences in S6 protein phosphorylation, cancer cell proliferation and eventually tumour size." (PMID 19436299, 2009). "A case study on NSCLC-specific SAS events, absent in healthy tissues, highlights their enrichment in cancer-related pathways like autophagy, GPI-anchor biosynthesis, and AMPK/mTOR signaling." (PMID 41749296, 2026). "Dual PI3K/mTOR inhibitors target both PI3K and mTOR signaling; however, none are currently FDA-approved for cancer treatment." (PMID 40657399, 2025).
cancer (continued). "Although the model was not developed for CRC, the mTOR pathway, in particular the PI3K/Akt/mTOR pathway, was extensively described as a potential target in this type of cancer." (PMID 40572223, 2025). "Cancer cells lacking the LKB1-AMPK axis rely on PROX1 to maintain intracellular BCAA levels, leading to enhanced mTOR signaling, tumorigenesis, and invasiveness." (PMID 40438606, 2025). "The TGF-β family is a well-established mediator of cancer stem cell potential and metastatic niches via either canonical Smad signaling or non-canonical pathways like PI3K/AKT/mTOR." (PMID 38689348, 2024). "Consistent with findings in other cancer types, our analysis revealed a negative correlation between PI3K/mTOR pathway over‐activation and TIL levels, implying that this pathway plays a role in T‐cell exclusion and immune evasion in (u)LMS." (PMID 38711203, 2024). "This revealed that MTOR, and to a lesser extent RPTOR and RICTOR, are indispensable for the survival of the majority of cancer cell lines, regardless of MYC amplification status." (PMID 37642941, 2023). "The allosteric mTOR inhibitors (e.g., everolimus, temsirolimus, and sirolimus) approved by the Food and Drug Administration (FDA) for human cancers can inhibit mTORC1 but have no obvious inhibiting effect on mTORC2." (PMID 38057772, 2023). "Epidemiologic evidence assessing PA levels and tumor mTOR and IGF pathway-related changes is not consistent across different cancer types and tissue markers." (PMID 36895729, 2023). "The 4 main signaling pathways previously implied to be linked to the impact of CR on life span, the insulin/ IGF-1, NF-ĸB, mTOR, and SIRT signaling pathways, showed no significant changes with the increase in CR level, neither did the pathways in cancer." (PMID 36757838, 2023). "Although there is no direct evidence that high expression of PD-L1 is simply mTOR-dependent, it is well known that AKT/mTOR pathway activation can promote the immune escape of cancer cells by promoting high PD-L1 expression." (PMID 36313041, 2022). "Recent studies demonstrate that oncogenic signaling pathways such as PI3K/AKT/mTOR, the epidermal growth factor receptor (EGFR), Ras/MAPK, Notch, and Wnt/β-catenin, play a fundamental role in cancer therapy." (PMID 35745567, 2022). "Unlike the Western diet, low-carbohydrate diets slow cancer by inhibiting insulin/IGF and downstream intracellular signaling pathways, specifically PI3K/Akt/mTOR." (PMID 35745105, 2022). "As for cancer research, the features regulating the opposing roles of PI3K/AKT/mTOR signalling have still not been plainly comprehended, and they deserve further studies." (PMID 35327539, 2022). "Although previous studies have shown that EVA1A regulates autophagy through ATG5 and mTOR/RPS6KB1 pathways in cancer, the mechanism of EVA1A regulating autophagy in cancer is not completely clear and needs to be further clarified." (PMID 35743108, 2022). "Many studies characterize the effect of mTOR, oncogenes, EIF4A, and EIF4E on translation; however, the specific effects arising from modulating 4EBP1 on mRNA translation in cancer are not well-defined." (PMID 35626002, 2022). "MAPK over-expression induced carcinogenic results through nonstandard activation of AKT/mTOR signals, while MAPK knockdown inhibited the proliferation of cancer cells." (PMID 33816226, 2021). "Among them, it induces the epithelial–mesenchymal transition (EMT) into non-tumour epithelial cells though the activation of mTOR and PI3K pathways, leading to the apoptosis resistance of cancer cells, and thereby promoting the trans-differentiation of CAFs." (PMID 34830058, 2021).